CTSB (cathepsin B)
Diseases named in the same sentence as CTSB in open-access papers (continued):
Sharing a sentence is not in itself a finding about the gene and the disease.
colorectal cancer (42 papers, 2000 to 2025). A primary or metastatic malignant neoplasm that affects the colon or rectum. "It is noteworthy that the overexpression of CTSL and CTSB has also been implicated in the progression of colorectal cancer." (PMID 31824841, 2019). "Cathepsin B has been reported to be associated with lymphatic metastasis in inflammatory breast cancer and is a prognostic marker in colorectal carcinoma." (PMID 24705283, 2014). "Furthermore, increased cathepsin B expression in the tumor epithelial cells of colorectal carcinomas was linked to a considerably reduced patient survival time." (PMID 36574159, 2022). "In addition, the combination of the two inhibitors, cystatin C and stefin A, could further stratify the risk of adverse event as was the case with stefin B and cathepsin B in colorectal cancer." (PMID 15138478, 2004). "In the case of colorectal cancer, CtsB plays a pivotal role in tumorigenesis, cell invasion, and metastasis, through both intra- and extra-lysosomal functions." (PMID 39851495, 2025). "Elevated cystatin C expression has been detected in colorectal cancer tissues compared to benign tissues, where increased cystatin C levels modulate cathepsin B—a lysosomal cysteine protease—promoting cancer invasion and basement membrane degradation." (PMID 41383336, 2025). "CTSB, a lysosomal cysteine protease, is highly overexpressed in various malignancies, such as breast, thyroid, liver, and colorectal cancers." (PMID 40756358, 2025). "This was thus achieved with supporting results of the high expression of germline variants in CTSB, and CPNE1 predicted in colorectal cancer." (PMID 38544823, 2024). "An overexpression of Cathepsin B as observed in MDA-MB-231, is associated with an increased cancer progression, namely growth, tumorigenesis, and invasion, as shown for colorectal cancer." (PMID 38896334, 2024). "Collectively, these studies underscore the significant role of cathepsin B levels/activity in predicting survival outcomes among colorectal cancer patients." (PMID 39001534, 2024). "CTSB has also been identified as a potential target for colorectal cancer therapy, owing to its ability to contribute to tumor development and invasion." (PMID 38544823, 2024). "The nano-sized RR–BA conjugate showed significant cathepsin B inhibitory effects and anticancer effects against mouse colorectal cancer (CT26) cells." (PMID 37111617, 2023). "In colorectal cancer, suppressing CTSB expression was found to downregulate Cyclin B1 and upregulate the Cyclin-CDK inhibitory protein P27kip1 in G2 phase, thereby inhibiting tumor growth." (PMID 37768200, 2023). "MM131 leads to the inhibition of important proteins engaged in the progression and metastasis of colorectal cancer such as sICAM-1, cathepsin B, and mTOR." (PMID 33918514, 2021). "The concentrations of important molecules (sICAM-1, mTOR, Beclin-1, cathepsin B) involved in the pathogenesis and poor prognosis of colorectal cancer were also evaluated by ELISA." (PMID 33918514, 2021). "Elevated expression of Cathepsin B protein was found in studies of breast, thyroid, and colorectal cancers." (PMID 32050622, 2020). "Cathepsin B cleaves cell cycle inhibitor p27Kip1 in the lysosomes of colorectal cancer cells, which contributes to tumorigenicity and metastasis of colorectal cancer cells." (PMID 32733461, 2020). "Nevertheless, in colorectal cancer tissues of less-advanced stages, cathepsin B is predominantly expressed by macrophages at the leading edge of invading tumors." (PMID 30818851, 2019). "As an intracellular lysosomal protease, cathepsin B has been found in the extracellular matrix (ECM) of colorectal cancer, localized to the invasive front of the tumor." (PMID 30949483, 2019). "Proteomic screening of tissue samples from colorectal cancer patients proved that cathepsin B was significantly upregulated in CRC tissue samples." (PMID 30818851, 2019).
colorectal cancer (continued). "Similarly, cathepsin B, an intracellular lysosomal cysteine protease, is markedly overexpressed in breast, thyroid, and colorectal cancers." (PMID 40871003, 2025). "Additionally, the concentration of important proteins (sICAM-1, mTOR, Beclin-1, cathepsin B) involved in the pathogenesis and poor prognosis of colorectal cancer was also evaluated by ELISA." (PMID 33918514, 2021). "Indeed, downregulation of cav-1 in colorectal carcinoma cells decreased trafficking of CTSB to caveolae on the surface of these cells and decreased degradation of ECM proteins and cellular invasion." (PMID 21199580, 2011). "In contrast, cathepsin B and L activities analysed in the same paired extracts had been shown to be most frequently elevated in earlier stage carcinomas (Dukes' A and B), confirming that cathepsin H demonstrates a distinct pattern of expression during colorectal cancer progression." (PMID 10755408, 2000). "With some of these results corroborating the outcomes of the present study, our study implicates CTSB and CPNE1 as important colorectal cancer indicators and suggests further experimental validation and comprehensive analysis for prospective studies." (PMID 38544823, 2024). "Of these, Cathepsin B (CTSB), Protein disulfide–isomerase (P4HB) and Cystatin-B (CSTB) were found upregulated in myeloma, lung cancer or colorectal cancer." (PMID 38791048, 2024). "In human colorectal cancer (CRC) cells, pro-cathepsin B interacts with the ANX II heterotetramer on the cell surface." (PMID 34462873, 2022). "A recent study identified CA-074Me as a specific cell-permeable CTSB inhibitor and small-molecule inhibitor diethyl-pythiDC that targets P4HA1 has been used for treating colorectal cancer." (PMID 34771678, 2021). "Studies showed Cathepsin B (CB)-activated polymeric probe, P-(GGFLGK-IR783), can detect the colorectal cancer as well as polyps in mice model." (PMID 34221964, 2021). "In particular, surface CTSB has been localized in caveolae in HUVEC endothelial and colorectal carcinoma cells." (PMID 33379277, 2020). "The elevation of CTSB and CTSD concentrations was shown in the sera of patients with some tumor types, including colorectal cancer, and bladder cancer." (PMID 26995190, 2016). "From this analysis, it is understood that two genes, CTSB and CPNE1, may tend to be more active in colorectal cancer cases than any other, implying further analysis into its use as a cancer indicator." (PMID 38544823, 2024). "Notably, the expression of CTSB in gastric and colorectal cancer correlates negatively with ECM, suggesting CTSB’s involvement in ECM remodeling." (PMID 39264885, 2024). "Notably, levels of cathepsin B have been shown to be increased in the tissues or serum of cancer patients diagnosed with CCA, thyroid cancer, or colorectal cancer." (PMID 39816815, 2023). "We want to investigate whether membrane CTSB localizes to caveolae, as described in HUVEC endothelial and human colorectal carcinoma cells." (PMID 33379277, 2020). "Furthermore, the authors, using a highly selective, non-permeant CtsB inhibitor, demonstrated that the extracellular activity of CtsB is key in promoting cancer cell migration and invasion, thus revealing a non-canonical, extralysosomal activity for CtsB in colorectal cancer metastasis." (PMID 39851495, 2025).
lung cancer (41 papers, 2004 to 2025). A malignant neoplasm involving the lung. "It was also shown that NEDD4 is important for lung cancer metastasis by increasing cathepsin B secretion or causing PTEN degradation." (PMID 36293239, 2022). "Our studies propose a novel mechanism underlying the EGFR-promoted lung cancer cell migration that is mediated by NEDD4 through regulation of cathepsin B secretion." (PMID 29455656, 2018). "Cathepsin B or cathepsin S has been implicated in the progression of various human cancers, including bladder, breast, prostate and lung cancers." (PMID 21595995, 2011). "Furthermore, a 1994 immunohistochemical study in Cancer found that higher-grade expression of cathepsin B was significantly linked to shorter survival in nonsmall cell lung cancer." (PMID 38500921, 2024). "It is reported that CTSB could influence the invasive activity of lung cancer and shows significant association with the development of oral squamous cell carcinoma (OSCC) and predicts an increased overall mortality risk of colon cancer." (PMID 33324676, 2020). "CTSB is highly-expressed in lung cancer and recruits monocytes into tumor to become TAMs, which promotes immunosuppression and tumor progression." (PMID 35277559, 2022). "Raised levels of cathepsin B have been found in metastatic malignant melanoma and lung cancer tissues of patients with hematogenous and intrapulmonary metastasis, and in tumor infiltrated lymph nodes." (PMID 34621666, 2021). "This study found that TSPN inhibited the expression of the CTSB gene and controlled the proliferation of tumors in lung cancer cells and the xenograft tumor model in mice." (PMID 33238959, 2020). "Overexpression or abnormal activity of CTSB has been previously reported in breast, pancreatic, liver, colorectal, oral, and lung cancer, and among others." (PMID 33333840, 2020). "Tub induced a significant increase in green fluorescence intensity; this indicates an increase in cathepsin B activity in the cytosolic fraction of lung cancer cells." (PMID 32848130, 2020). "The NAC treatment reversed the LMP increase as well as increased cytosolic cathepsin B activity in Tub-induced lung cancer cells." (PMID 32848130, 2020). "The level of cathepsin B significantly increased in the cytosolic fraction of lung cancer cells after Tub treatment." (PMID 32848130, 2020). "Recently, a mechanism of cathepsin B release followed by enhanced lung cancer cell migration was proposed, indicating a possible role in the progression of lung cancer." (PMID 30897858, 2019). "The specific cathepsin B inhibitor CA-074Me was used for assessing the role of cathepsin B in lung cancer cell migration." (PMID 29455656, 2018). "NEDD4 mediates the EGFR lung cancer cell migration signaling through promoting lysosomal secretion of cathepsin B." (PMID 29455656, 2018). "In this proposed pathway, the NEDD4-dependent secretion of the lysosomal cathepsin B is a key step for lung cancer cell migration." (PMID 29455656, 2018). "Further studies on these pathways in future are necessary for elucidation of the mechanism by which NEDD4 promotes secretion of cathepsin B and the lung cancer cell migration." (PMID 29455656, 2018). "In lung cancer patients, cathepsin B expression was shown to be a prognostic marker of shorter overall survival." (PMID 28076408, 2017). "Retrospective immunohistochemical analysis showed that lung cancer patients with upregulated CTSB tend to have higher rates of hematogenous and intrapulmonary metastases." (PMID 26995190, 2016). "Since these observations were made before the clinical onset of cachexia, it is suggested that similar to findings from animal models, cathepsin B expression is involved in the induction of cachexia in lung cancer patients." (PMID 26856534, 2016).
lung cancer (continued). "Matrigel invasion assay showed the invasive capacity of lung cancer cells decreased nearly 80% after treatment with CTSB-shRNA." (PMID 24139065, 2013). "The results showed that the invasive capacity of lung cancer cells decreased nearly 80% after treatment with CTSB-shRNA by quantitative analysis." (PMID 24139065, 2013). "Increased levels of CTSB have been reported in several cancers, but relatively little is known about CTSB’s involvement in lung cancer proliferation and apoptosis." (PMID 24139065, 2013). "More recently, lung cancer patients undergoing resection were shown to have increased levels of cathepsin B mRNA in skeletal muscle compared with controls." (PMID 20193046, 2010). "However, a study of lung cancer patients referred for curative resection and with a weight loss of only 2.9% showed no increase in expression of components of the ubiquitin-proteasome pathway, while mRNA levels of cathepsin B in skeletal muscle were much higher." (PMID 16160695, 2005). "For example, in mouse and cell experiments, it was found that CTSB knockout or inhibition can improve the progression of a variety of diseases, such as acute myelogenous leukemia, lung cancer, pancreatitis, a variety of neurological diseases and myocardial injury." (PMID 40457023, 2025). "The results of this study demonstrate that treating A549 cells with 10 μg/mL FNE can significantly reduce the expression levels of three key proteins involved in the pathogenesis of lung cancer, specifically in cancer invasion and metastasis: CTSB, enolase, and GAL3." (PMID 39574963, 2024). "Previous studies reported elevated levels of cathepsin B and L in lung cancer patients." (PMID 37805623, 2023). "The microtubule-destabilizing chemotherapeutic agent Vinblastine produced a response similar to that of BMPR2 inhibition with an increase in lysosome acidification, cytosol localization, and increase in Cathepsin B activity in lung cancer cells and MDA-MB-468 cells." (PMID 34563224, 2021). "Furthermore, we found that NEDD4 promotes lung cancer cell migration by facilitating the EGFR-dependent lysosomal secretion of cathepsin B." (PMID 34833029, 2021). "CTSB gene was closely related to the pathogenesis of lung cancer." (PMID 33238959, 2020). "This indicated that PNS might inhibit the proliferation and invasion of the tumor through the CTSB gene and prolong the survival time of mice with lung cancer, providing an experimental basis for treating lung cancer using Panax notoginseng." (PMID 33238959, 2020). "This study aimed to investigate the mechanism of action of Panax notoginoside (PNS) against lung cancer and inhibition of lung cancer cell proliferation by the drug at different concentrations in a mouse model, considering the cathepsin B (CTSB) gene as a target." (PMID 33238959, 2020). "Furthermore, the E3 ubiquitin ligase NEDD4 interacted with EGFR, which mediated lung cancer cell migration through activating CTSB." (PMID 32331211, 2020). "PNS could act on the CTSB gene, downregulate the expression of CTSB in lung cancer cells, inhibit the proliferation and invasion of tumors, and prolong the survival period." (PMID 33238959, 2020). "CTSB protein and CTSB mRNA were highly expressed in lung cancer." (PMID 33238959, 2020). "Thus, it is likely that NEDD4 mediates the EGFR cell migration signaling in lung cancer cell lines through activation of the lysosomal cathepsin B secretion pathway." (PMID 29455656, 2018). "Furthermore, knockdown of NEDD4 inhibits EGF-dependent unconventional lysosomal cathepsin B secretion, which is an important cellular process for lung cancer cell migration." (PMID 29455656, 2018). "In addition, lung cancer patients with upregulated CTSB tended to exhibit a higher rate of hematogenous and intrapulmonary metastasis." (PMID 27031837, 2016). "The results above demonstrated CTSB influenced the metastatic capacity of lung cancer cells." (PMID 24139065, 2013).
lung cancer (continued). "Furthermore, it has been shown that the serum level of cathepsin B/cystatin C complexes was significantly decreased in patients with malignant lung tumours than in healthy controls." (PMID 15138478, 2004). "Furthermore, the results of reverse MR analyses indicated that squamous cell carcinomas increase cathepsin B expression, explaining the high levels of cathepsin B detected in lung cancer patients in previous clinical studies and elucidating the unique role of squamous cell carcinomas." (PMID 37805623, 2023). "Also, CTSB was proved to be closely related to the pathogenesis of lung cancer in a mouse model." (PMID 35494076, 2022). "Thus, CTSB cannot directly affect proliferation and apoptosis of lung cancer cells." (PMID 24139065, 2013). "The protein expression of CTSB and CTSE in lung cancer tissues from the KMS group was found to be lower than that in the KS group, as evidenced by western blotting and immunohistochemistry (IHC) analyses." (PMID 40057469, 2025). "In lung cancer cell lines, we also observed that SP2509 restored the expression of CTSB, LC3B, and TFAM, which were suppressed by MEN1-KD." (PMID 40057469, 2025). "Although the result of the present study shows that 10 μg/mL of fisetin nano emulsion can significantly reduce the expression levels of relevant markers such as CTSB, enolase, and GAL3 in lung cancer cells, we also have several limitations to consider." (PMID 39574963, 2024). "Through stimulation of the lysosomal cathepsin B secretion pathway, NEDD4 can also mediate EGFR cell migration signaling in lung cancer cell lines." (PMID 36293239, 2022). "When BMPR2 activity was inhibited with JL5, Ym155, or siRNA knockdown of BMPR2, lysosomal activity was increased in lung cancer cells as demonstrated by an increase in lysosome acidification, LAMP1 expression, and Cathepsin B activity." (PMID 34563224, 2021). "Consistent with the role of NEDD4, cathepsin B is pivotal for both basal and the EGF-stimulated lung cancer cell migration." (PMID 29455656, 2018). "Western blotting analysis showed that MEN1 shRNA-knockdown (KD) noticeably inhibited the expression of both the precursor (p) and mature (m) forms of CTSB and CTSE in the lung cancer cell lines (A549 and NCI-H157) and the immortalized bronchial epithelial cell line (16-HBE)." (PMID 40057469, 2025). "The decrease in cathepsin B and cathepsin D activities without any effects on autophagosome-lysosome fusion increases the cytotoxicity of cisplatin and paclitaxel in the lung cancer cells." (PMID 35387352, 2022). "In addition, studies have indicated that CTSB and CTSS mediate cancer progression and metastasis in lung cancer, renal cancer, and gastric cancer." (PMID 32331211, 2020). "To confirm the role of NEDD4 in lysosomal secretion, we detected the secreted lysosomal protease cathepsin B in culture medium using an ELISA assay in both the vector control and the shNEDD4 lung cancer A549 cells with or without EGF stimulation." (PMID 29455656, 2018). "A previous study found that the expression of CTSB significantly reduced after using TSPN at different concentrations to treat lung cancer A549 cells, suggesting TSPN in A549 cells could promote apoptosis and inhibit cell proliferation via inhibiting the expression of the CTSB gene." (PMID 33238959, 2020). "However, in skeletal muscle of patients with early stages of lung cancer, mRNA levels of the lysosomal proteases cathepsin B and D were elevated, whereas components of the UPS were not increased." (PMID 26856534, 2016). "The lysosomal protease cathepsin B is important for both the EGF and the non-EGF dependent lung cancer cell migration." (PMID 29455656, 2018). "To connect the NEDD4-mediated lung cancer cell migration, including both the EGF and the non-EGF dependent lung cancer cell migration, to lysosomal secretion, we examined the effect of CA-074Me, a specific inhibitor of cathepsin B, on lung cancer A549 cell migration using a wound healing assay." (PMID 29455656, 2018).